YTHDF3 (YTH N6-methyladenosine RNA binding protein F3)
Diseases named in the same sentence as YTHDF3 in open-access papers (continued):
Sharing a sentence is not in itself a finding about the gene and the disease.
pancreatic cancer (continued). "Further, we design a biologically active YTHDF3-derived peptide to competitively inhibit YTHDF3 palmitoylation mediated by ZDHHC20, which in turn downregulates MYC expression and inhibits the progression of KRAS mutant pancreatic cancer." (PMID 38821916, 2024). "Furthermore, we noted that YTHDF3 overexpression partially rescued celastrol-induced downregulation of Claspin and Bcl-2, and abrogated the celastrol-mediated suppression of cell proliferation and cell cycle progression, and the induction of apoptosis in celastrol-treated in pancreatic cancer cells." (PMID 38110764, 2023). "Collectively, these results suggested that YTHDF3/DICER1-AS1/DICER1/miR-5586-5p axis is pivotal for glycolysis and tumorigenesis of pancreatic cancer." (PMID 35183226, 2022). "It has been reported that YTHDF3 is overexpressed in multiple kinds of tumors and promotes tumor progression, but its regulatory role in pancreatic cancer has not been explored." (PMID 38821916, 2024).
hepatocellular carcinoma (10 papers, 2021 to 2025). A malignant tumor that arises from hepatocytes. "Zinc finger protein 41 (ZFP41) can suppress the progression and metastasis of hepatocellular carcinoma, and YTHDF3-catalyzed m6A modification of ZFP41 suppresses hepatocellular carcinoma malignant progression by attenuating Snail transcriptional activation." (PMID 40986143, 2025). "YTHDF3 binds to and degrades ZFP41 mRNA, inhibiting the Snail and EMT pathways and thus suppressing hepatocellular carcinoma metastasis." (PMID 40774945, 2025). "This suggests that YTHDF3 and PFKL work together to produce a positive feedback loop that controls the metabolism of cancer cells in hepatocellular carcinoma." (PMID 40919129, 2025). "Furthermore, research in hepatocellular carcinoma has revealed a connection between EFTUD2 and metabolic reprogramming, where EFTUD2 regulates the protein stability of YTHDF3, an m6A “reader” protein involved in RNA metabolism." (PMID 40650074, 2025). "In addition, YTHDF3 increases the stability and translation of m6A-methylated EGFR transcripts and drives hepatocellular carcinoma advancement." (PMID 40986143, 2025).
asthma (9 papers, 2021 to 2025). "m6A methylation is also implicated in the emergence and evolution of asthma, with the most crucial regulatory factor being the YTHDF3 enriched at exon 3′‐UTR, which has an impact on asthma related eosinophils." (PMID 38706740, 2024). "The m6A methylation has also been implicated in the pathogenesis of asthma, and YTHDF3 has an effect on eosinophils for severe asthma, which can guide future immunotherapy strategies." (PMID 36553648, 2022). "By applying univariate logistic regression and LASSO Cox regression models, they identified YTHDF3 and YTHDC1 as key m6A regulators significantly associated with severe asthma." (PMID 41008562, 2025). "Another study on severe asthma found 16 regulators differentially expressed, and two key m6A regulators (YTHDF3 and YTHDC1)." (PMID 37328853, 2023). "The results showed that the expression of known m6A writers (i.e., METTL3 and METTL14), erasers (i.e., FTO and ALKBH5), and readers (i.e., YTHDF3) was moderately downregulated in peripheral blood mononuclear cells (PBMCs) of human asthma sufferers." (PMID 37957139, 2023). "We examined the expression data of the 16 difference‐expressed genes using univariate logistic regression to identify the potential m6A regulators, and two regulators (YTHDF3 and YTHDC1) were found to be associated with severe asthma." (PMID 34647423, 2021). "Besides, it was found that the eosinophils which are very important for severe asthma were affected by YTHDF3 and EIF3B." (PMID 34647423, 2021). "The results also revealed that YTHDF3 and EIF3B affected the infiltration of eosinophils, which are vital in severe asthma." (PMID 37328853, 2023). "They found abnormal expression of YTHDF3 and YTHDC1 in many severe asthma patients, suggesting alterations in the immune microenvironment and influencing eosinophil activity relevant to severe asthma." (PMID 39135292, 2024). "Correlation analyses also revealed strong interactions between YTHDF3, YTHDC1, and other m6A machinery components, indicating that their cooperative activity may contribute to immune dysregulation and the pathogenesis of severe asthma." (PMID 41008562, 2025). "m6A-seq and MeRIP-qPCR findings indicate that m6A /METTL3/YTHDF3 interactions are involved in the repression of M2 macrophage activation by accelerating the degradation of Pentraxin 3 (PTX3) transcripts, which is widely regarded as a regulator of inflammation and asthma." (PMID 37957139, 2023). "Considered together, the m6A regulators YTHDF3, YTHDC1, WTAP, FTO, METTL3, and ETTL14 may have a significant effect on the prognosis of asthma, but studies on m6A methylation, severe asthma, and the prognosis of asthma are still in the initial stage and require further exploration by researchers." (PMID 39108751, 2024).
melanoma (9 papers, 2021 to 2026). A malignant, usually aggressive tumor composed of atypical, neoplastic melanocytes. "LOXL3 downregulation inhibited the metastatic ability of melanoma cells, and overexpression of LOXL3 ameliorated the inhibition of melanoma metastasis caused by YTHDF3 downregulation." (PMID 36324258, 2022). "Therefore, we explored the methylation recognition protein YTHDF3 and its underlying mechanism in the biological behaviour of melanoma." (PMID 36324258, 2022). "RBM15, VIRMA, IGF2BP3, and YTHDF3 were frequently overamplified in melanoma patients, while VIRMA displayed missense mutations with unknown significance." (PMID 34446007, 2021). "However, reports associated with m6A, especially in melanoma were mainly focused on m6A writers and erasers, only one report demonstrated that YTHDF3‐CTNNB1 axis could affect the biological process of ocular melanoma." (PMID 36324258, 2022). "Conversely, overexpression of LOXL3 reduces the suppressive effect of YTHDF3 knockdown on melanoma metastasis." (PMID 41250755, 2025). "Mechanistically, YTHDF3 has been found to facilitate the translation of Catenin Beta 1 (CTNNB1), a driver gene implicated in melanoma genesis, via an m6A-dependent mechanism." (PMID 39342406, 2024). "More specific role of m6A readers like YTHDF3 in tumourigenesis of melanoma, especially cutaneous melanoma, was elusive." (PMID 36324258, 2022). "Via various results of public datasets, we noticed that in the GEPIA dataset, only YTHDF3 had a significantly higher expression in melanoma tissues." (PMID 36324258, 2022). "Among various targets identified by multi‐omics analysis, LOXL3 stood out as an optimal target of YTHDF3 in melanoma." (PMID 36324258, 2022). "Downregulation of YTHDF3 induced the inhibition of migration and invasion of melanoma cells determined by transwell assay and wound healing experiment in A375, SK‐MEL‐28 and A2058 cells." (PMID 36324258, 2022). "We consistently noticed that YTHDF3 had a higher expression in melanoma and metastatic melanoma among different datasets." (PMID 36324258, 2022). "We found that YTHDF3 was highly expressed in melanoma tissues and melanoma cells, and, the protein level of YTHDF3 was high in these cell lines detected by Western blot." (PMID 36324258, 2022). "We performed RT‐qPCR to compare the RNA level of YTHDF3 in melanoma tissues and adjacent tissues, epidermal melanocytes and various melanoma cell lines." (PMID 36324258, 2022). "In this study, we found that YTHDF3 was highly expressed in melanoma tissues and cell lines compared with benign nevi samples or epidermal melanocytes." (PMID 36324258, 2022). "Immunohistochemical results revealed that YTHDF3 was highly expressed in melanoma tissue samples compared with benign nevi tissues." (PMID 36324258, 2022). "With the help of shRNAs (shYTHDF3‐1 and shYTHDF3‐2), we downregulated YTHDF3 in melanoma cells including A375, SK‐MEL‐28 and A2058 cells." (PMID 36324258, 2022). "Collectively, these results demonstrated that via its m6A binding sites, LOXL3 not only had an oncogenic role in the migration and invasion of melanoma but served as an important ‘executor’ of YTHDF3." (PMID 36324258, 2022). "By searching on some online bioinformatic websites and previous reports, we found that YTHDF3 was highly expressed in melanoma tissues compared with para‐tumour tissues and benign nevi." (PMID 36324258, 2022). "Collectively, our work revealed the regulatory role of YTHDF3 in the migration, invasion and metastasis of melanoma cells both in vitro and in vivo." (PMID 36324258, 2022). "Although these readers could also have a significant expression in some of these datasets, only YTHDF3 had a consistent significant expression in all datasets, indicating that YTHDF3 may play a vital role in determining the metastatic behaviour of melanoma." (PMID 36324258, 2022).
melanoma (continued). "To determine whether YTHDF3 could affect malignant behaviour such as migration and invasion of melanoma, we conducted a related experiment in vitro." (PMID 36324258, 2022). "YTHDF3 regulates migration, invasion and metastasis of melanoma cells both in vitro and in vivo." (PMID 36324258, 2022). "Compared with primary melanoma, YTHDF3 was highly expressed in metastatic or invasive melanoma." (PMID 36324258, 2022). "In this study, we found that m6A reader YTHDF3 could affect the metastasis of melanoma both in vitro and in vivo." (PMID 36324258, 2022). "Also, we confirmed that YTHDF3 has an impact on the metastasis of melanoma both in vitro and in vivo." (PMID 36324258, 2022). "Hence, we confirmed that YTHDF3 plays a role in regulating melanoma invasion and metastasis both in vitro and in vivo." (PMID 36324258, 2022). "Using RIP‐qPCR, we further confirmed that YTHDF3 could catch these transcripts except PDE3A in SK‐MEL‐28 melanoma cells." (PMID 36324258, 2022). "Besides, it was found that compared with primary melanoma, the YTHDF3 expression was higher in metastatic melanoma." (PMID 36324258, 2022). "Additionally, YTHDF2 and YTHDF3 facilitated melanoma progression through distinct mechanisms." (PMID 41301778, 2025). "Therefore, the evidence of whether YTHDF3 could have a more robust or independent regulatory role in melanoma was inadequate." (PMID 36324258, 2022). "We discovered that N6-methyladenosine (m6A) modulators-specifically YTHDF3, YTHDC1, and METTL14-cooperatively upregulate BGN expression in a parallel, non-hierarchical manner converging on functional m6A sites within melanoma cells." (PMID 41833003, 2026). "High expression levels of YTHDF3 have been observed in melanoma cancer stem cells (CSC), and the knock-down of YTHDF3 has been found to significantly inhibit tumor proliferation and migration, emphasizing its critical involvement in these processes." (PMID 39342406, 2024). "Our study revealed the oncogenic role of YTHDF3 and its target LOXL3 in melanoma metastasis and its specific mode of action." (PMID 36324258, 2022). "Similar to the expression of YTHDF3, an increased mRNA and protein level of LOXL3 in melanoma cells compared with epidermal melanocytes." (PMID 36324258, 2022). "To better understand the role of LOXL3 and its function regulated by YTHDF3, we reversed the expression of LOXL3 in YTHDF3‐ downregulation (shYTHDF3‐1) A375, SK‐MEL‐28 and A2058 melanoma cells." (PMID 36324258, 2022). "In GEO datasets, except YTHDC2, other m6A readers like YTHDF1, YTHDF2, YTHDF3 and YTHDC1 have a significant higher expression in melanoma tissues." (PMID 36324258, 2022). "RT‐qPCR, Western blot and immunohistochemistry were conducted to measure the expression level of YTH N6–methyladenosine RNA binding protein 3 (YTHDF3) and lysyl oxidase–like 3 (LOXL3) in melanoma tissues and cells." (PMID 36324258, 2022). "It was found that after reversing the expression of LOXL3, the migration and invasion of YTHDF3‐downregulation A375, SK‐MEL‐28 and A2058 melanoma cells were recovered to some extent, which were identified by transwell assay and wound healing experiment." (PMID 36324258, 2022). "YTHDF3 and its downstream LOXL3 play a critical role in melanoma metastasis and could serve as a potential therapeutic target to be intervened." (PMID 36324258, 2022). "The effects of YTHDF3 and LOXL3 on melanoma were verified in vitro and in vivo." (PMID 36324258, 2022).
cervical cancer (8 papers, 2022 to 2025). A primary or metastatic malignant neoplasm involving the cervix. "In our previous research, we observed a marked increase in YTHDF3 expression in cervical cancer, promoting lymph node metastasis by reprogramming fatty acid metabolism." (PMID 41453852, 2025). "This regulatory mechanism involving YTHDF3-mediated HR pathway-based DNA damage repair contributes to the modulation of radiation resistance in cervical cancer." (PMID 38651153, 2024). "YTHDF3-mediated upregulation of m6A modifications promotes fatty acid metabolism and promotes lymphatic metastasis of cervical cancer by activating the LRP6-YAP-VEGF-C axis." (PMID 38651153, 2024). "We revealed higher levels of ZC3H13, WTAP, HNRNPC, YTHDF3, and VIRMA were significantly associated with worse outcomes in CESC (HR > 1, blue background), while YTHDC1, YTHDF1 were protective factors of cervical cancer (HR < 1, orange background)." (PMID 35581263, 2022). "PD-L1 expression increased dramatically in cervical cancer tissues and was significantly linked to ALKBH5, FTO, METTL3, RBM15B, YTHDF1, YTHDF3, and ZC3H13 expression levels." (PMID 36091006, 2022). "To clarify the mechanism underlying the YTHDF3 upregulation in CCa, we employed a combination of RNA-seq and ATAC-seq analysis in three cell lines: HFF-1 (Human epithelial foreskin fibroblasts cell line), H8 (immortal cervical epithelium cell line), and SiHa (cervical cancer cell line)." (PMID 38250152, 2024). "For example, YTHDF3 facilitated HDAC6 translation, ultimately attenuating cell growth and cervical cancer development." (PMID 40406242, 2025). "Mechanistic exploration demonstrated YTHDF3 knockdown potently induced IFN-α and IFN-β mRNA overexpression in cervical cancer cells." (PMID 41453852, 2025). "As a result, in line with the oncogenic role of the METTL3/HDAC6 axis, higher expression of both METTL3, YTHDF3, and HDAC6 was observed in tumor tissues when compared to the matched adjacent normal tissues from cervical cancer patients." (PMID 39535388, 2025). "YTHDC1 and YTHDF1 have anti-cancer effects in cervical cancer, while ZC3H13, WTAP, HNRNPC, YTHDF3 and VIRMA have tumor-promoting effects in cervical cancer." (PMID 35581263, 2022). "In addition, survival analysis showed that cervical cancer patients with increased expression of METTL3, YTHDF3, and HDAC6 represented an obviously unsatisfied overall survival (OS)." (PMID 39535388, 2025).
liver cancer (7 papers, 2020 to 2025). An epithelial or non-epithelial malignant neoplasm that arises from the liver. "For example, the overexpression of YTHDF3 in liver cancer is associated with poor prognosis, and knockdown of YTHDF3 inhibits lung metastasis and HCC cell proliferation." (PMID 40271153, 2025). "The results demonstrated that lower YTHDF3 expression was associated with a poorer response to sorafenib in liver cancer (higher IC50 and AUC)." (PMID 39629121, 2024). "Other m6A methylation readers, such as YTHDF3 and IGF2BP1/2/3, are closely linked to immune therapy in liver cancer." (PMID 39911396, 2025). "Surprisingly, PFKL positively regulates the expression of YTHDF3 protein, forming a positive feedback loop of YTHDF3-PFKL-YTHDF3, promoting the growth and lung metastasis of liver cancer." (PMID 37582735, 2023). "In liver cancer, high expression of writer, reader, and eraser proteins was associated with poor survival except METTL3, YTHDF3 and ALKBH5." (PMID 32863943, 2020). "YTHDF3 has significant regulatory functions, as it precisely controls the translation efficiency of immune-related mRNA, thereby profoundly influencing the complex and delicate interactions between immune cells and liver cancer cells." (PMID 39911396, 2025).
gastric cancer (6 papers, 2020 to 2025). A primary or metastatic malignant neoplasm involving the stomach. "In non-small cell lung cancer, YTHDF3 promotes immune suppression via PD-L1 upregulation, while in gastric cancer, it activates PI3K/AKT signaling and alters the tumor immune microenvironment." (PMID 40565233, 2025). "Low expression of YTHDF3 was associated with poor OS (P = 0.000016) and PPS (P = 1 x 10-8) in gastric cancer." (PMID 36606187, 2022).
bladder cancer (5 papers, 2020 to 2025). "YTHDF3, as one of ‘readers’ of m6A RNA modification, can recognize residues of m6A in ITGA6 and increase ITGA6 expression to promote bladder cancer occurrence." (PMID 33829656, 2021). "Studies also found that YTHDF1/YTHDF3 can preferentially identify the m6A-modified region in the 3 untranslated regions of ITGA6, promoting ITGA6 translation and enhancing the growth and metastasis of bladder cancer cells." (PMID 34604051, 2021).
lung carcinoma (5 papers, 2021 to 2023). "As predicted on the Kaplan-Meier plotter website, low expression of YTHDF3 was associated with poor OS in lung cancer (P = 0.000018)." (PMID 36606187, 2022). "In contrast, high expression of YTHDF3 was associated with poor post-progression survival (PPS) in lung cancer (P = 0.000074)." (PMID 36606187, 2022). "As reported by Jin, YTHDF1 and YTHDF2 interacted competitively with YTHDF3 to module YAP expression in lung cancer in an m6A-independent manner." (PMID 36870954, 2023). "To validate the involvement of YTHDF3 and IGF2BP1 in the regulation of JUN and JUNB expression, we confirmed the knockdown effects in protein and mRNA expression in A549 and LC2/ad lung cancer cells with or without TGF-β treatment." (PMID 36183833, 2022). "Previously, studies have investigated the role of thirteen m6A regulatory genes in lung cancer, but the roles of seven newly discovered ones, namely, METTL16, YTHDF3, IGF2BP1, IGF2BP2, IGF2BP3, HNRNPG, and HNRNPA2B1 has not been determined." (PMID 33795529, 2021).
ocular melanoma (5 papers, 2022 to 2023). A melanoma that arises from the structures of the eye or ocular adnexa. "It was recently reported that YTHDF3 expression was associated with ocular melanoma and poor patient outcomes." (PMID 36606187, 2022). "Until now, only one report demonstrated that the YTHDF3‐CTNNB1 axis participated in the tumourigenicity of ocular melanoma." (PMID 36324258, 2022). "YTHDF3 is highly expressed in ocular melanoma tissues, which is related to poor clinical prognosis." (PMID 36835633, 2023). "YTHDF3 is required for the maintenance of cancer stem cell (CSC) properties and tumor initiation in ocular melanoma." (PMID 36835633, 2023). "YTHDF3 promotes the translation of the catenin beta 1 (CTNNB1) and contributes to ocular melanoma propagation." (PMID 36835633, 2023).
triple-negative breast carcinoma (5 papers, 2021 to 2024). An invasive breast carcinoma which is negative for expression of estrogen receptor (ER), progesterone receptor (PR), and human epidermal growth factor receptor 2 (HER2). "High expression of YTHDF3 is associated with poor disease-free survival and overall survival in triple-negative breast cancer patients." (PMID 39062595, 2024). "Interestingly, in triple-negative breast cancer cells, YTHDF3 was involved in EMT, cell migration, and invasion." (PMID 36183833, 2022). "YTHDF3 can enhance ZEB1 mRNA stability in an m6A-dependent manner, thereby promoting the migration, invasion, and metastasis of triple-negative breast cancer." (PMID 39062595, 2024). "For example, YTHDF3 positively regulates NSCLC cells’ migration, invasion, and EMT in triple-negative breast cancer cells through enhancing ZEB1 mRNA stability in an m6A-dependent manner." (PMID 38992016, 2024). "Six paired samples from two luminal B, two Her2 enriched, and two triple-negative breast cancer (TNBC) patients were used for IHC of METTL3, METTL14, FTO, YTHDF1, and YTHDF3." (PMID 34804948, 2021).